KLF14 (KLF transcription factor 14)
Diseases named in the same sentence as KLF14 in open-access papers (continued):
Sharing a sentence is not in itself a finding about the gene and the disease.
cervical cancer (continued). "In this study, we investigated whether KLF14 can inhibit the proliferation and promote the apoptosis of cervical cancer cells." (PMID 35570248, 2022). "We demonstrated the role of KLF14 in promoting apoptosis of cervical cancer cells." (PMID 35570248, 2022). "Moreover, ITGB1 inhibited apoptosis and reversed the effect of KLF14 on cervical cancer cell apoptosis." (PMID 35570248, 2022). "In addition, the apoptosis rate of cervical cancer cells treated with Lv-KLF14 + Lv-ITGB1 was lower than that of cervical cancer cells treated with Lv-KLF14 + Lv-control (ITGB1)." (PMID 35570248, 2022). "On this basis, we considered whether KLF14 might be associated with ITGB1, thereby affecting the development of cervical cancer." (PMID 35570248, 2022). "This revealed that KLF14 could inhibit ITGB1 expression in cervical cancer cells at the protein level." (PMID 35570248, 2022). "At present, there are relatively few studies on the role of KLF14 in cervical cancer." (PMID 35570248, 2022). "The presence of zinc fingers in KLF14 promotes S-phase arrest in cervical cancer cells, and we postulate that this aspect will generate a basis for targeted therapy in cervical cancer and a theoretical platform for the development of cervical cancer biopharmaceuticals." (PMID 38143751, 2023). "Therefore, we considered that KLF14 might associate with ITGB1 to promote the apoptosis of cervical cancer cells, thereby inhibiting the development of cervical cancer." (PMID 35570248, 2022). "KLF14 may be a potential and noteworthy target in the treatment of cervical cancer." (PMID 35570248, 2022). "The results suggest that KLF14 promoted JNK-pathway activation to induce S-phase arrest and promote the expression of CDK2 and CCNA2 in cervical cancer cells." (PMID 38143751, 2023). "This demonstrated that inhibition of JNK-pathway activation reversed KLF14-induced CDK2 and CyclinA2 protein expression in cervical cancer cells." (PMID 38143751, 2023). "Previous studies of my research group found that KLF14 targets ITGB1, promotes apoptosis through the PI3K/AKT signaling pathway, and inhibits the progression of cervical cancer." (PMID 38143751, 2023). "Third, to further prove the relationship between KLF14 and ITGB1 and their effects on cervical cancer, we conducted functional experiments." (PMID 35570248, 2022). "First, Western blotting was performed to verify that when KLF14 was overexpressed, ITGB1 expression was downregulated in cervical cancer SiHa and HeLa cells." (PMID 35570248, 2022). "KLF14 promotes JNK-pathway activation and expression of CDK2 and CyclinA2 in cervical cancer cells." (PMID 38143751, 2023). "When extracted mRNA from the cells of the different groups for qRT-PCR, we observed that the expression of CDK2 mRNA in the OE-KLF14 group was increased compared with the control group (PSiHa<0.001, PHeLa<0.001), indicating that KLF14 promoted the expression of CDK2 mRNA in cervical cancer cells." (PMID 38143751, 2023). "After SP600125 treatment, the CDK2 mRNA expression level in the OE-KLF14+S group was lower than its control group (all P<0.001), indicating that inhibition of JNK-pathway activation reversed KLF14-induced CDK2 mRNA expression in cervical cancer cells." (PMID 38143751, 2023). "CDK2 protein expression was increased in the OE-KLF14 group compared with the control group (PSiHa=0.043, PHeLa<0.001), and CyclinA2 protein expression was increased (PSiHa=0.012, PHeLa=0.015), showing that KLF14 promoted CDK2 and CyclinA2 protein expression in cervical cancer cells." (PMID 38143751, 2023). "The results of the present study further showed that KLF14 induces S-phase arrest in cervical cancer and activates the JNK pathway to promote the expression of CDK2 and CCNA2 in cervical cancer cells, with its zinc fingers participating in the induction of S-phase arrest." (PMID 38143751, 2023).
cervical cancer (continued). "Moreover, Flow cytometry was performed to verify the relationship between KLF14 and ITGB1 on the apoptosis of cervical cancer cells." (PMID 35570248, 2022). "We considered that the proliferation of cervical cancer cells may be associated with the activation of the PI3K/AKT signaling pathway, so the relationship between the PI3K/AKT pathway, KLF14 and HPV-positive cervical cancer is worthy of further study." (PMID 35570248, 2022). "First, the KLF14 expression levels of cervical cancer cells were not compared with those of normal cervical cells due to the difficulty in obtaining normal cervical cells." (PMID 35570248, 2022). "At the same time, we found that the effects of KLF14 and ITGB1 on apoptosis of cervical cancer cells could be mutually affected." (PMID 35570248, 2022). "Moreover, we further explored whether KLF14 regulates CDK2 and CyclinA2, and plays an inhibitory role in the progression of cervical cancer by regulating the JNK/MAPK signaling pathway." (PMID 38143751, 2023). "Therefore, we considered whether KLF14, CDK2, CyclinA2 and MAPK signaling pathways are correlated to affect the cell cycle of cervical cancer." (PMID 38143751, 2023). "Nevertheless, KLF14 simultaneously suppresses cervical cancer progression by inhibiting integrin beta 1 transcription, which upregulates key molecules in the PI3K/AKT signaling, including AKT and p-AKT, representing an indirect inhibitory effect of KLF14 on PI3K/AKT." (PMID 36761967, 2023). "Therefore, we considered whether KLF14, ITGB1 and PI3K/AKT signaling pathways are correlated to affect the progression of cervical cancer." (PMID 35570248, 2022). "Moreover, we further explored whether KLF14 regulates ITGB1 and plays an inhibitory role in the progression of cervical cancer by regulating the PI3K/AKT signalling pathway." (PMID 35570248, 2022). "Therefore, we believe that KLF14 and ITGB1 may be correlated and affect the development of cervical cancer through the PI3K/AKT signalling pathway." (PMID 35570248, 2022). "In addition, flow cytometry showed that KLF14-overexpressing cervical cancer cells had a higher rate of apoptosis than negative control cells, which confirmed the role of KLF14 in promoting apoptosis of cervical cancer cells." (PMID 35570248, 2022). "However, the effect and mechanism of KLF14 on the cervical cancer cell cycle have not been unclear." (PMID 38143751, 2023).
colon cancer (4 papers, 2015 to 2023). "Overexpression of KLF14 led to G2/M arrest, and KLF14 acted as a tumour suppressor in breast ductal carcinoma and colon cancer." (PMID 34031939, 2021). "Clinically, KLF14 transcription is significantly downregulated, whereas Plk4 transcription is upregulated in multiple types of cancers, and there exists an inverse correlation between KLF14 and Plk4 protein expression in human breast and colon cancers." (PMID 26439168, 2015). "Indeed, many KLF14-KO mice developed spontaneous tumours and KLF14 depletion enhances AOM/DSS-induced colon tumour formation in vivo." (PMID 26439168, 2015). "Moreover, low KLF14 transcription is ubiquitously coupled with high Plk4 transcription in multiple forms of human cancers and there is a significant inverse correlation between the protein levels of KLF14 and Plk4 in human breast and colon cancers." (PMID 26439168, 2015). "Research suggested that the aberrant expression of transcription factors such as KLF14 and SOX2 in colon cancer can affect the occurrence and progression of colon cancer by affecting the expression of downstream genes." (PMID 36755247, 2023). "Further analysis of human breast and colon cancer samples reveal that KLF14 protein expression is significantly decreased, whereas Plk4 expression is significantly increased, and a strong negative association exists between Plk4 and KLF14 expressions in the tumour tissues." (PMID 26439168, 2015). "However, no spontaneous breast and colon tumours were observed in KLF14-KO mice." (PMID 26439168, 2015).
liver fibrosis (4 papers, 2021 to 2025). "KLF14 expression was critical to maintaining hepatic gluconeogenesis and reducing hepatic fibrosis in male mice." (PMID 40790397, 2025). "Adenovirus‐mediated KLF14 overexpression ameliorated TAA‐induced rat liver fibrosis in PPARγ‐dependent manner." (PMID 34031939, 2021). "More importantly, there existed a strongly positive correlation between KLF14 expression and PPARγ expression in patients with liver fibrosis." (PMID 34031939, 2021). "As the severity of liver fibrosis progressed, the mRNA and protein levels of KLF14 decreased dramatically, accompanied by upregulation of α‐SMA." (PMID 34031939, 2021). "Taken together, KLF14 overexpression transactivated PPARγ, and therefore converting the activated HSCs to the quiescent phenotype, thus alleviating liver fibrosis." (PMID 34031939, 2021). "Collectively, our study suggests that KLF14 overexpression mitigates TAA‐induced rat liver fibrosis through PPARγ signalling." (PMID 34031939, 2021). "Upon HSCs activation, the elevated EZH2 mediates suppression of KLF14 expression, which promotes HSCs activation and liver fibrosis by downregulating PPARγ." (PMID 34031939, 2021). "To study the function of KLF14 in liver fibrosis, we examined KLF14 expression in TAA‐induced rat liver fibrotic model and CCl4‐induced mouse liver fibrotic model." (PMID 34031939, 2021). "In animal studies, adenovirus‐mediated KLF14 overexpression ameliorated thioacetamide (TAA)‐established rat liver fibrosis through activating PPARγ signalling." (PMID 34031939, 2021). "The results demonstrated that TAA administration induced liver fibrosis, however, KLF14 overexpression alleviated the severity of fibrosis, which was represented by H&E, Masson's trichrome, Sirius red, and α‐SMA staining." (PMID 34031939, 2021). "Collectively, these findings suggest that KLF14 suppression due to EZH2 elevation in fibrotic liver contributes to liver fibrosis progression by downregulating PPARγ." (PMID 34031939, 2021). "In vivo, KLF14‐overexpressing adenovirus was injected via tail vein to thioacetamide (TAA)‐treated rats to investigate the role of KLF14 in liver fibrosis progression." (PMID 34031939, 2021). "Moreover, EZH2-mediated inhibition of KLF14 expression via H3K27me3 promoted hepatic stellate cell activation and liver fibrosis." (PMID 35264108, 2022). "Considering the vital role of KLF14 in proliferation, survival, migration and lipid metabolism, we surmised that KLF14 might regulate biological processes of HSCs, and therefore regulating liver fibrosis." (PMID 34031939, 2021). "Collectively, EPZ‐6438 could alleviate TAA‐induced liver fibrosis by directly regulated PPARγ expression and indirectly regulated PPARγ expression via KLF14." (PMID 34031939, 2021). "We thought these results could at least confirm the existence of the indirect regulation, as we have confirmed KLF14 overexpression did alleviate liver fibrosis in vitro and in vivo." (PMID 34031939, 2021). "In summary, we reported a protective role for KLF14 in liver fibrosis." (PMID 34031939, 2021). "Krüppel‐like factor 14 (KLF14) regulates various biological processes, however, roles, mechanisms and implications of KLF14 in liver fibrosis are unknown." (PMID 34031939, 2021). "Furthermore, KLF14 expression was negatively correlated with EZH2 expression in patients with liver fibrosis." (PMID 34031939, 2021). "By using PPARγ antagonist GW9662 and specific LV‐shRNA, we found that PPARγ inhibition significantly decreased the inhibitory roles of KLF14 overexpression in HSCs, and in vivo study confirmed that KLF14 overexpression ameliorated TAA‐induced liver fibrosis in PPARγ‐dependent manner." (PMID 34031939, 2021). "Collectively, these clinical and experimental evidences strongly indicated that KLF14 exerted profound protective roles in liver fibrosis, and these effects could be achieved at least through direct regulation of HSCs and hepatoprotective activities." (PMID 34031939, 2021).
liver fibrosis (continued). "In this study, we reported that KLF14 was decreased in liver fibrosis and during HSCs activation." (PMID 34031939, 2021). "The EZH2 inhibitor EPZ‐6438 rescues EZH2‐mediated KLF14 downregulation, which transactivates PPARγ expression, converts the activated HSCs to the quiescent phenotype and induces apoptosis, and therefore alleviating liver fibrosis." (PMID 34031939, 2021). "Importantly, KLF14 expression was decreased in human with liver fibrosis, which was significantly correlated with EZH2 upregulation and PPARγ downregulation." (PMID 34031939, 2021). "Collectively, KLF14 expression is inversely correlated with liver fibrosis and HSCs activation, which might play a role in liver fibrogenesis." (PMID 34031939, 2021). "Moreover, KLF14 could transactivate PPARγ promoter activity to ameliorate liver fibrosis, of which PPARγ played an important role in regulating cell proliferation and cell senescence." (PMID 37551728, 2023). "Thus, KLF14 exerts a critical role in liver fibrogenesis, and targeting the EZH2/KLF14/PPARγ axis might provide a novel approach to liver fibrosis treatment." (PMID 34031939, 2021). "Furthermore, adenovirus‐mediated KLF14 overexpression ameliorated TAA‐induced rat liver fibrosis." (PMID 34031939, 2021). "KLF14 reversed the activated HSCs to the quiescent phenotype and inhibited TAA‐induced liver fibrosis by transactivating PPARγ expression." (PMID 34031939, 2021). "Taken together, these results demonstrated that EZH2 inhibitor EPZ‐6438 upregulated KLF14 expression and ameliorated TAA‐induced rat liver fibrosis." (PMID 34031939, 2021). "KLF14 exerts a critical anti‐fibrotic role in liver fibrosis, and targeting the EZH2/KLF14/PPARγ axis might be a novel therapeutic strategy for liver fibrosis." (PMID 34031939, 2021). "Next, we investigated whether KLF14 regulated hepatic fibrogenesis in vivo, we ectopically enforced the KLF14 expression in a TAA‐induced rat liver fibrosis model by injecting KLF14‐expressing adenovirus via tail vein, with or without PPARγ inhibition by intraperitoneal GW9662 administration." (PMID 34031939, 2021). "Considering KLF14 overexpression inhibited liver fibrosis in vitro and in vivo, and KLF14 expression was robustly reactivated upon EPZ‐6438 in vitro treatment, we aimed to investigate whether in vivo administration of EPZ‐6438 affected the progression of liver fibrosis." (PMID 34031939, 2021).
Alzheimer disease (2 papers, 2018 to 2020). A progressive, neurodegenerative disease characterized by loss of function and death of nerve cells in several areas of the brain leading to loss of cognitive function such as memory and language. "They reported aberrant hypermethylation and decreased prediction accuracy of chronological age for TRIM59 and KLF14 markers in the group of early onset Alzheimer’s disease." (PMID 32661599, 2020). "Therefore, based on the transcriptomic data of fEOAD patients, in this study, we present the genetic networks for hypermethylated KLF14 and TRIM59 with their downstream signaling pathways, potentially relevant in the pathology of Alzheimer's disease." (PMID 29849909, 2018).
brain cancer (2 papers, 2022 to 2023). A primary or metastatic malignant neoplasm affecting the brain. "The outcomes of the current study highlighted the diagnostic potential of co-expression of KLF14, PKCε, TPD52 and miR-124 in brain cancer." (PMID 35577881, 2022). "TPD52 and PKCε were upregulated in brain cancer by 2.5- and 1.6-fold, respectively, whereas, KLF14 and miR-124 were downregulated in brain cancer." (PMID 35577881, 2022). "Therefore, the main aim of this study was to investigate the gene expression levels and possible correlation between PKCε, TPD52, miR-124 and KLF14 to improve understanding of their contribution in the development of brain cancer and neoplasm lesions." (PMID 35577881, 2022). "Differential expression analysis of TPD52, PKCε, KLF14 and miRNA 124 in brain cancer subtypes: astrocytomas, glioblastomas, and oligodendrogliomas revealed that the expression of TPD52 and PKCε was up regulated in glioblastomas compared to astrocytomas and oligodendrogliomas." (PMID 35577881, 2022). "The present study also demonstrated the novel finding of lower expression of KLF14 in space occupying lesion (SOL) of brain compared to healthy controls; however, KLF14 expression in blood of brain cancer patients was lower than that observed in SOL patients." (PMID 35577881, 2022). "The study aimed to investigate the possible relation of KLF14, TPD52, miR-124, and PKCε in the development and progression of brain cancer and space occupying lesion (SOL) of the brain." (PMID 35577881, 2022). "In metastatic and high-grade brain cancer, TPD52 and PKCε expression were up-regulated and KLF14 and miR-124 expression were down-regulated." (PMID 35577881, 2022).
brain tumors (2 papers, 2022 to 2023). "The analysis revealed that the value for KLF14 and miR-124 in predicting risk of brain tumor is high with Area under the Curve (AUC) 0.86 and 0.84, respectively." (PMID 35577881, 2022). "KLF6 expression is elevated in ovarian malignancies, KLF8 promotes cellular proliferation in HCC, gastric, and glioma carcinomas, while KLF3 and KLF14 have been reported to inhibit tumor growth in breast and brain tumors, respectively." (PMID 37833790, 2023). "Studies delineating TPD52, KLF14 and PKCε expression in brain tumours and space occupying lesions (SOL) of brain are also scarce." (PMID 35577881, 2022). "This study reported that the expression of KLF14 in brain tumours is down-regulated as compared to healthy controls suggesting its expression is necessary for the normal functioning of brain." (PMID 35577881, 2022). "KLF14 expression variation was also observed in different brain tumour grades." (PMID 35577881, 2022). "In lower grade of brain tumours (I + II), its expression is higher than the advanced grade tumours (III + IV), suggesting the continuous reduction of KLF14 expression in brain tumours may lead towards the high-grade cancer." (PMID 35577881, 2022).
breast ductal carcinoma (2 papers, 2015 to 2021). "Results showed that there were significantly lower protein levels of KLF14, but higher levels of Plk4, in cancer tissues of breast ductal carcinomas as compared with the adjacent normal tissues." (PMID 26439168, 2015).
cardiac hypertrophy (2 papers, 2023 to 2025). "Moreover, KLF14 knockout mice showed accelerated age-related cognitive decline, hair loss, cardiac hypertrophy, and increased tissue fibrosis and exhibited higher rates of mortality." (PMID 39857283, 2025). "Cardiac hypertrophy in the heart, inflammatory infiltration, and vacuolation in the liver, inflammatory infiltration, and glomerular sclerosis in the kidney were also observed in 6‐ and 11‐month‐old KLF14 knockdown mice." (PMID 37551728, 2023).
familial Alzheimer disease (2 papers, 2020 to 2021). A degenerative disease of the brain that causes gradual loss of memory, judgment, and the ability to function socially. "Moreover, TRIM59 and KLF14 hypermethylation in blood cells may be a valuable predictor of the molecular processes underlying familial Alzheimer’s disease." (PMID 32020847, 2020). "Moreover, the KLF14 gene was under a hypermethylation state in familial Alzheimer's disease, which regulated cell death signalling." (PMID 34031939, 2021).
Glucose intolerance (2 papers, 2023). Glucose intolerance (GI) can be defined as dysglycemia that comprises both prediabetes and diabetes. "In support of these in vitro findings, overexpression of KLF14 in healthy mice lowered glucose tolerance, and knockdown of KLF14 in db/db mice attenuated glucose intolerance." (PMID 36902112, 2023).